GSDMD (gasdermin D)
Diseases named in the same sentence as GSDMD in open-access papers (continued):
Sharing a sentence is not in itself a finding about the gene and the disease.
bladder cancer (9 papers, 2020 to 2025). "This is the first study to assess the diagnostic relevance of serum gasdermin D in bladder cancer patients." (PMID 39766111, 2024). "Some studies have suggested that the expression of gasdermin D in bladder cancer cells could be associated with the progression of the disease." (PMID 39766111, 2024). "Till now, only one publication demonstrated that GSDMD may be implicated in the etiology and severity of bladder cancer." (PMID 36120543, 2022). "GSDMD has been implicated in the etiology and severity of bladder cancer in a few publications." (PMID 36120543, 2022). "For instance, GSDMD has been suggested as a marker of bladder cancer and non-alcoholic steatohepatitis (NASH)." (PMID 37685853, 2023). "In contrast, bladder cancer tissue sections of the NMIBC group showed a noticeable cytoplasmic expression of GSDMD, and this expression is increasing with the higher stages showing a strong expression in the MIBC tissue samples." (PMID 36120543, 2022). "This study aimed to investigate GSDMD gene expression in bladder cancer tissue samples in comparison to control samples to assess its potential role in pathogenesis and aggressiveness of bladder cancer, thus the role of GSDMD as a new possible target for management of bladder cancer." (PMID 36120543, 2022). "The Univariate Cox regression analysis revealed that eight PRGs (PRKACA, GSDMB, CASP9, GSDMD, CASP6, CASP8, AIM2, and CASP1) were significantly correlated with the prognosis in bladder cancer." (PMID 36120583, 2022).
cardiac hypertrophy (9 papers, 2021 to 2024). "Pharmacological inhibition of GSDMD and GSDMD-mediated inflammation by DL-3-n-butylphthalide suppressed cardiac hypertrophy in the mouse model of transverse aortic constriction." (PMID 39253076, 2024). "During angiotensin II or pressure-overload-induced cardiac hypertrophy, GSDMD generates a positive feed-forward amplification loop through the mitochondria-STING axis." (PMID 39253076, 2024). "Recently, studies have suggested that GSDMD deficiency reduces hypertrophy and pyroptosis in cardiomyocytes induced by Ang II or TAC in mice, while GSDMD and STING knockout reduce cardiac hypertrophy in mice overexpressing GSDMD in cardiac muscle." (PMID 38067543, 2023). "Accordingly, in uremic cardiomyopathy, increased levels of caspase-1, IL-1β, IL-18, and cleaved gasdermin D p30 protein, the active form of gasdermin D, induced myocardial hypertrophy, interstitial fibrosis, and functional alterations in the heart." (PMID 37958859, 2023). "Our study shows that NBP attenuates myocardial hypertrophy by targeting GSDMD and inhibiting GSDMD-mediated inflammation." (PMID 34168567, 2021). "Cardiac hypertrophy significantly increased the proportion of apoptotic cells and upregulated apoptosis-associated speck-like protein containing a CARD (ASC), caspase-1, and gasdermin D (GSDMD)." (PMID 39553724, 2024). "And after inhibiting GSDMD, Ang II-induced cardiac hypertrophy was significantly alleviated." (PMID 35360548, 2022). "Using molecular docking and MD simulation, we detected that the GSDMD-N protein may be a target of NBP, indicating that NBP mimics a selective GSDMD inhibitor in preventing cardiac hypertrophy." (PMID 34168567, 2021). "Thus, we hypothesized that pressure overload may induce myocardial hypertrophy through GSDMD and GSDMD-mediated inflammation." (PMID 34168567, 2021). "The increase in pyroptosis in myocardial hypertrophy was accompanied by enhanced regulation of NLRP3, caspase-1, ASC, and GSDMD." (PMID 39553724, 2024). "In addition, NBP engages GSDMD-N protein, a key executioner of pyroptosis, and decreases its expression in cardiomyocytes, which may inhibit the process of GSDMD-N gathering to form pores in the membrane, indicating that targeting GSDMD might be a new strategy for treating myocardial hypertrophy." (PMID 34168567, 2021). "Moreover, it was reported that GSDMDNT was significantly activated, but full-length GSDMD was reduced in the hearts of 16-week-old male diabetic db/db mice with significant cardiac hypertrophy." (PMID 38067543, 2023).
E. coli infection (9 papers, 2018 to 2025). "Instead, GSDMD-mediated neutrophil death dampens the bactericidal activity against the E. coli infection, and the delayed neutrophil death in GSDMD-deficient mice results in enhanced host defense." (PMID 31035661, 2019). "In support of these results, we found that exogenous SAA1 potentiated the secretion of caspase-11 and GSDMD cleavage from BMDMs upon E. coli infection." (PMID 38297162, 2024). "Mechanistically, our results suggest the involvement of the NLRP3/caspase-1/GSDMD pathway in E. coli infection." (PMID 37511208, 2023). "Our results showed that NLRP3, caspase-1, GSDMD, and IL-1β were significantly upregulated in response to E. coli infection, with KEGG enrichment revealing that upregulated genes were mainly concentrated in the NOD-like receptor signaling pathway." (PMID 37511208, 2023). "Protein interaction network analysis revealed that the pyroptosis classic pathway NLRP3/caspase-1/GSDMD is involved in E. coli infection." (PMID 37511208, 2023). "We also investigated the mRNA levels of the genes involved in the NLRP3/caspase-1/GSDMD pathway in cells after E. coli infection and found that ZB-1 infection significantly upregulated their expression levels." (PMID 37511208, 2023). "Next, we measured the mRNA levels of each gene in the NLRP3/caspase-1/GSDMD pathway after E. coli infection." (PMID 37511208, 2023). "For example, Gsdmd-deficient mice exhibited delayed neutrophil death and enhanced cytotoxic activity against Escherichia coli infection in vivo, further corroborating the GSDMD role for fine-tuning the immune response." (PMID 35844522, 2022). "To further elucidate the mechanism of pyroptosis induced by E. coli infection, we mined the dataset (GSE124917) in the GEO database and found that E. coli infection significantly upregulates NLRP3, caspase-1, GSDMD, and IL-1β." (PMID 37511208, 2023). "In validation experiments, chimeric mice with nonhematopoietic caspase-1 or GSDMD knockout were protected from lung E. coli infection and exhibited decreased neutrophil death." (PMID 40359428, 2025).
glioblastoma (9 papers, 2021 to 2025). The most malignant astrocytic tumor (WHO grade IV). "In the SRA PRJNA482620 glioblastoma (GBM) cohort, which includes 66 patients treated with standard therapy and PD-1 inhibitors (nivolumab or pembrolizumab), higher GSDMD expression was associated with poorer overall survival (HR = 3.0719, p = 0.032)." (PMID 40491921, 2025). "Another study demonstrated on a model of human glioblastoma cells that ZIKV is also able to induce caspase-independent pyroptosis, provided by ZIKV NS2B3, which directly cleaves the GSDMD into N-terminal fragment." (PMID 36016430, 2022).
Hyperglycemia (9 papers, 2021 to 2025). An increased concentration of glucose in the blood. "The GSDMD gene plays a critical role in mediating pyroptosis, a form of apoptosis induced by hyperglycemia." (PMID 40562805, 2025). "has also suggested that the cleavage of GSDMD by caspase-1 is downstream to hyperglycemia-induced oxidative stress in H9c2 cardiomyoblasts." (PMID 39253076, 2024). "A recent study reported that empagliflozin reduced the diabetic pancreatic tissue from hyperglycemia-induced damage of db/db mice via the suppression of the NLRP3/caspase-1/GSDMD pathway." (PMID 35265148, 2022). "Moreover, hyperglycemia activated the NLRP3/caspase-1/GSDMD axis to cause pore formation, where GSDMD further aggravated pyroptosis in human retinal pericytes." (PMID 39253076, 2024). "Correspondingly, the GSDMD expression was increased during hyperglycemia." (PMID 35265148, 2022). "In addition, EMD treatment was confirmed to rescue normal shape and function of INS-1 cells during hyperglycemia via the inhibition of NLRP3/GSDMD signaling, suggesting EMD could regulate the upstream of GSDMD cleavage and suppress pyroptosis." (PMID 35265148, 2022). "The mechanism of how hyperglycemia activates ALPK1 and how ALPK1-NF-κB signal pathway activates GSDMD-related canonical pyroptosis are unclear." (PMID 36732854, 2023). "In the current study, both GSDMD and GSDME were increased in the high-glucose-treated retinal vascular endothelial cells, which is consistent with previous findings, indicating that hyperglycemia can trigger pyroptosis in retinal vascular endothelial cells." (PMID 35957838, 2022). "In conclusion, hyperglycemia activates ALPK1 in renal TECs, leading to phosphorylation of NF-κB, which could contribute to release of the N-terminal domain of GSDMD after cleavage by caspase-1." (PMID 36732854, 2023).
osteoarthritis (9 papers, 2021 to 2026). A noninflammatory degenerative joint disease occurring chiefly in older persons, characterized by degeneration of the articular cartilage, hypertrophy of bone at the margins and changes in the synovial membrane. "The unexpected outcomes with the STIA model prompted us to determine the role of GSDMD in the post-traumatic osteoarthritis (PTOA) model caused by meniscus ligamentous injury (MLI) based on the hypothesis that this pore-forming protein is activated by signals released from damaged joint tissues." (PMID 34784954, 2021). "In summary, in mice, GSDMD was dispensable in the K/BxN model of RA, but it showed protection in a post-traumatic osteoarthritis model, and chemical inhibition of GSDMD by DSF protects mice upon type-II collagen-induced arthritis induction." (PMID 35455985, 2022). "Moreover, several researches in osteoarthritis indicated that GSDMD-mediated FLSs pyroptosis participates in HIF-1α-induced synovial fibrosis in knee osteoarthritis." (PMID 35237610, 2021). "In inflammatory conditions, GBP5 promotes chondrocyte pyroptosis by upregulating pyroptosis-related genes, such as NLRP3, Caspase-1, and Gasdermin D (GSDMD), through the NLRP3 inflammasome pathway, contributing to osteoarthritis progression." (PMID 40788157, 2025). "In osteoarthritis, moderate-intensity exercise reduces inflammation and pyroptosis by increasing the expression of Metrnl, an adipomyokine that inhibits the PI3K/Akt/NF-κB signaling pathway and subsequently the NLRP3/caspase-1/GSDMD pathway." (PMID 41399377, 2026).
bacterial sepsis (8 papers, 2019 to 2026). "Since GSDMD is a direct inflammasome target for execution of this pathway, as observed in inflammasome-deficient mice, Gsdmd disruption also inhibits bacterial sepsis in which cytokines facilitate septic shock." (PMID 34795266, 2021). "Specifically, GSDMD pores trigger lung inflammation via alveolar macrophage pyroptosis, induce hepatic high mobility group box 1 protein (HMGB1) release, perpetuate bacteremia, cause renal microthrombosis, and disrupt the blood-brain barrier." (PMID 42094003, 2026). "Correspondingly, GSDMD−/− mice exhibited significantly enhanced survival rates and diminished myocardial injury in the setting of lethal bacterial sepsis." (PMID 41345109, 2025). "In addition, STING was also reported to trigger calcium dependent GSDMD activation in bacterial sepsis." (PMID 41463428, 2025). "Thus, for bacterial sepsis where IL-1β facilitates septic shock, inhibition of GSDMD-mediated pore formation is considered an effective therapeutic strategy to prevent early shock caused by systemic hyperinflammation." (PMID 34795266, 2021). "Similarly, we recently demonstrated that during bacterial sepsis and neutrophils stimulated with bacteria (Streptococcus pneumoniae or Staphylococcus aureus), as shown in the present study, the NET production is dependent on GSDMD activation." (PMID 35799268, 2022). "Internalized LPS activates the noncanonical caspase-11 inflammasome, which cleaves Gasdermin D (GSDMD), leading to the generation of GSDMD N-terminal fragments (GSDMD-NT) and subsequent pyroptosis in bacterial sepsis." (PMID 35095914, 2021).
diabetic cardiomyopathy (8 papers, 2022 to 2024). Diabetic cardiomyopathy is a disorder of the heart muscle in people with diabetes. "Studies have discovered the occurrence of GSDMD-dependent cell pyroptosis in a mouse model of diabetic cardiomyopathy." (PMID 37418795, 2023). "GSDMD-mediated pyroptosis was found downstream to mitochondrial dysfunction and ROS in diabetic cardiomyopathy mice in a cGAS/STING-dependent manner, however, we cannot exclude the possibility that GSDMD might generate a feedforward loop by forming pores on mitochondria." (PMID 39253076, 2024). "In addition, some studies have shown that AIM2 plays an important role in myocardial cell death and fibrosis through the GSDMD pathway in high glucose-induced ROS-mediated diabetic cardiomyopathy, and inhibition of AIM2 expression reduces progression of diabetic cardiomyopathy (DCM)." (PMID 36993972, 2023). "In this study, we found that miR-223-3p, as a regulator of the pyroptosis molecule NLRP3, is downregulated in the myocardium of diabetic cardiomyopathy mice, but significantly increased after MSC treatment, thereby reducing the protein levels of NLRP3, Caspase-1, GSDMD, and IL-1β." (PMID 38956716, 2024).
experimental autoimmune encephalomyelitis (8 papers, 2019 to 2023). An autoimmune demyelinating disease of the central nervous system that is produced experimentally in animals by the injection of homogenized brain or spinal cord in Freund's adjuvant. "A previous study showed that GSDMD-KO mice had lower clinical scores than their WT counterparts in an experimental autoimmune encephalomyelitis model." (PMID 35669106, 2022). "Indeed, GSDMD-mediated pyroptosis is involved in neuroinflammation of experimental autoimmune encephalomyelitis (EAE) model, which is initiated by peripheral myeloid cells." (PMID 35962439, 2022). "Evidence for GSDMD-mediated pyroptosis in human macrophages/microglia in vitro and in MS patient white matter was reported previously; likewise, GSDMD immunoreactivity and pyroptosis have been observed in myeloid-lineage cells in the murine CNS during experimental autoimmune encephalomyelitis (EAE)." (PMID 32861242, 2020).
influenza (8 papers, 2019 to 2026). An acute viral infection of the respiratory tract, occurring in isolated cases, in epidemics, or in pandemics; it is caused by serologically different strains of viruses (influenzaviruses) designated A, B, and C, has a 3-day incubation period, and usually lasts for 3 to 10 days. "Severe influenza was also associated with increased expression of cleaved GSDMD, which colocalized with CD163 and with cytokeratin, reflecting pyroptosis of macrophages and alveolar epithelial cells respectively." (PMID 35271686, 2022). "Another study using the HKx31 influenza model found that GSDMD-/- mice had attenuated lung inflammation along with reduced airspace neutrophil infiltration, suggesting that GSDMD may be an underlying trigger of excessive damaging neutrophilic inflammation." (PMID 39823516, 2025). "In support of this notion, recent work has indicated that inflammasome activation may underlie deleterious neutrophil functions with Gasdermin D (GSDMD) knockout mice protected from influenza-induced mortality despite similar viral loads and lung neutrophil recruitment compared to wild-type." (PMID 39823516, 2025). "Cleaved GSDMD colocalized with macrophages and alveolar epithelial cells and with viral NP protein in lung sections of macaques with lethal influenza, consistent with pyroptosis of infected cells." (PMID 35271686, 2022). "As such, GSDMD may be a new candidate therapeutic target for treatment of influenza and to improve disease outcomes." (PMID 37945599, 2023). "In contrast, genes associated with pyroptosis, including CASP4, NLRP3 and GSDMD, were highly expressed in whole lung lysates from macaques with lethal influenza but not from uninfected animals." (PMID 35271686, 2022). "Targeting the GSDMD/neutrophil axis may provide a therapeutic avenue for treating severe influenza." (PMID 38553499, 2024). "In contrast, full-length and fully cleaved caspase-4, as well as full-length and cleaved GSDMD, were readily detected in BAL fluid from macaques with severe influenza." (PMID 35271686, 2022). "Cleaved-PARP1 increased dose-dependently, while p-MLKL and cleaved-GSDMD showed no consistent trends, indicating that apoptosis was the major pathway triggered by influenza infection in A549 cells." (PMID 41258714, 2026). "Collectively, these studies point to the detrimental role of GSDMD- and GSDME-mediated pyroptosis in IAV infection and suggest that targeting GSDMD and/or GSDME may provide a novel therapeutic option for treating severe influenza infection." (PMID 41011440, 2025). "BBR has been shown to improve lung inflammation in influenza mice by inhibiting NACHT, LRR, and PYD domains-containing protein 3 (NLRP3) inflammasome activation and inhibiting GSDMD-mediated apoptosis by reducing GSDMD expression and suppressing NLRP3 inflammasome-mediated GSDMD activation." (PMID 40076449, 2025). "Finally, we examined the expression of Il-1β and cleaved GSDMD in lung and its relationship to macrophages (CD163+) and alveolar epithelial cells (cytokeratin+) in uninfected macaques and those with lethal influenza by immunohistochemistry." (PMID 35271686, 2022). "Recent studies have indicated that inflammasome activation by GSDMD is instrumental in the development of neutrophilic pathology in murine influenza models, as GSDMD-/- mice are protected from PR8 influenza and do not show greater benefits with neutrophil depletion as the wild-type mice do." (PMID 39823516, 2025). "While necroptosis was suggested to perform such a role upon infection with Influenza, MNV did not provoke MLKL-mediated membrane permeability but rather induced GSDMD-mediated pyroptosis." (PMID 31017981, 2019).
osteosarcoma (8 papers, 2021 to 2026). A usually aggressive malignant bone-forming mesenchymal neoplasm, predominantly affecting adolescents and young adults. "The expression of GSDMD is significantly upregulated in osteosarcoma and is associated with drug resistance and poor prognosis in osteosarcoma patients, providing new insights into the diagnosis and prognosis prediction of osteosarcoma." (PMID 38304430, 2024). "Studies have shown that GSDMD was notably upregulated in osteosarcoma compared to normal skeletal tissue as well as associated with drug resistance and prognosis for patients with osteosarcoma." (PMID 34899864, 2021). "Compared with normal tissues, the expression of GSDMD in osteosarcoma is relatively high, which can independently indicate the prognosis status of patients with osteosarcoma." (PMID 34381721, 2021). "NLRP3 inhibition influences the biological behaviors of osteosarcoma via the NLRP3/Caspaseaspase-1/GSDMD pathway." (PMID 34393801, 2021). "Consistent with the role of GSDMD in LUAD and osteosarcoma, our evidence shows that GSDMD was a novel oncogene and prognostic biomarker for LGG patients and GBM patients." (PMID 34830775, 2021). "Researchers have produced dichloroacetate polymer micelles (OPDEA-PDCA) that can induce mitochondrial oxidative stress by inhibiting pyruvate dehydrogenase kinase 1 (PDHK1), leading to GSDMD-mediated pyroptosis of osteosarcoma cells and enhancing osteosarcoma immunotherapy." (PMID 38304430, 2024). "Suppression of NLRP3 protein by its targeted inhibitor CY-09 or knockdown of the NLRP3 gene could inhibit the cell proliferation, migration, invasion, promote apoptosis and G0/G1 cell cycle arrest in osteosarcoma cells in vitro via NLRP3/Caspase-1/GSDMD pathway." (PMID 34393801, 2021). "Therefore, NLRP3/Caspase-1/GSDMD pathway may be involved in NLRP3-induced carcinogenesis of osteosarcoma." (PMID 34393801, 2021). "The present results of the western blot revealed that the NLRP3 as well as caspase-1, GSDMD, IL-1β, and IL-18 proteins decreased after NLRP3 blockage in osteosarcoma." (PMID 34393801, 2021).